TNF (tumor necrosis factor)
Diseases named in the same sentence as TNF in open-access papers (continued):
Sharing a sentence is not in itself a finding about the gene and the disease.
Obesity (continued). "However, regression analysis did not support that these two inflammatory markers were independently associated with the HOMA-IR and DIOGTT, indicating that elevated TNFα and CRP may play a role by mediating other risk factors for T2D such as obesity." (PMID 28713332, 2017). "TNF stimulation of differentiated 3T3-L1 cells, mimicking part of the M1 macrophage-induced inflammatory response, decreased Paral1 expression, suggesting that obesity-induced inflammation may regulate Paral1 expression." (PMID 29075020, 2017). "Previous research has demonstrated that TNFα can interfere with insulin mediated glucose metabolism in neonatal porcine adipose tissue, thereby creating an insulin resistant state that is characteristic of adipose tissue inflammation in obesity, diabetes and metabolic syndrome." (PMID 27087941, 2016). "Thus, the effect of exercise on serum TNF-α is dependent upon the intensity of exercise, whether it is a single bout or habitual and also to some extent on the obesity level of the participants." (PMID 26925234, 2016). "Obesity-induced increased levels of glucose and FFAs create stress in pancreatic islets, adipose tissue, liver, and muscle, resulting in increased local production and release of cytokines and chemokines such as IL-1β, TNFα, CCL2, CCL3, and CXC-chemokine ligand 8 (CXCL8, also known as IL-8)." (PMID 28018292, 2016). "The association between Lequesne index and leptin was highly increased in the two models when the effect of leptin was not controlled by anthropometric or inflammatory variables, indicating that the pathway of leptin in clinical severity could be shared by TNF-α and obesity." (PMID 27629533, 2016). "Obesity is often accompanied by low-grade chronic inflammation in adipose tissues, and exhibiting elevated pro-inflammatory cytokines such as tumor necrosis factor-α (TNF-α), interleukin-1β (IL-1β), interleukin-6 (IL-6) and monocyte chemotactic protein-1 (MCP1)." (PMID 26837433, 2016). "Considering the effects of TNF on L cells and data from animal models, indicating that impaired glucose tolerance following high-fat diet-induced obesity can be ameliorated by anti-TNF therapy, one might expect a significant impact of anti-TNF treatment on glucose metabolism." (PMID 27148273, 2016). "During the early stages of mild obesity in mice fed a high-fat diet (HFD), obesity not only stimulates infiltration of M1 macrophages, which gives rise to the proinflammatory environment, but also alters secretion of chemokines and cytokines such as TNF-α and IL-6." (PMID 27101398, 2016). "WAT releases hormones (leptin, adiponectin, etc.)and cytokines (tumor necrosis factor-α (TNF-α), interleukin 6 (Il-6), monocyte chemoattractant protein-1 (Mcp-1), etc.)that modulate whole-body metabolism, insulin resistance, and the systemic low-grade inflammation associated with obesity." (PMID 28105413, 2016). "Additionally, some other mechanisms are known, including dysfunction in the renin-angiotensin-aldosterone system, increased tubular sodium reabsorption, and the effects of obesity-related hormones and cytokines such as leptin, adiponectin and Tumor Necrosis Factor-α." (PMID 27832768, 2016). "In addition, TNF-α decreases adiponectin secretion and stimulates production of other proinflammatory substances such as IL-6, thus contributing to the maintenance of chronic inflammatory of adipose tissue observed in obesity." (PMID 27213076, 2016). "Serum TNF-α was 5.5 ± 0.6 pg/ml in HFD- fed C57BL/6J mice (P < 0.01) vs 2.6 ± 0.3 pg/ml in SRC-fed C57BL/6J mice and was 6.7 ± 0.8 pg/ml in HFD- fed KKAy mice (P < 0.01) vs 3.2 ± 0.4 pg/ml in SRC-fed KKAy mice, indicating a role of overweight- or obesity-associated inflammation in carcinogenesis." (PMID 27528218, 2016). "Also, no obvious association was found between the TNF-alpha (−308 G/A) polymorphism and obesity in patients with PCOS (body mass index [BMI] ≥ 25 kg/m2 vs. BMI < 25 kg/m2)." (PMID 25634659, 2015).
Obesity (continued). "In addition to fat cells, it has been shown that in obesity white adipose tissue is infiltrated by macrophages, which may also be a major source of proinflammatory cytokines, TNF-α, IL-6, MCP-1 and iNOS." (PMID 26247962, 2015). "Whether the positive effect of OA and HT on adiponectin is accounted for by the inhibition of other TNF-α-triggered intracellular pathways relevant to obesity (such as ceramide biosynthesis, endoplasmic reticulum stress, and mitochondrial dysfunction), also deserves further evaluation." (PMID 26030149, 2015). "It was reported that treatment with cytokines TNF-α or IL-6 in cultured pig hepatocytes decreased apoA-IV mRNA levels, suggesting that the cytokines may contribute to dietary-induced obesity through down-regulation of the important satiety signal apoA-IV expression." (PMID 25861245, 2015). "We hypothesize that increased maternal obesity-induced inflammation suppresses development of the DA neural circuit, as treatment with inflammatory cytokines, interleukin-6, IL-1β, and tumor necrosis factor-α, decrease the survival of DA neurons in the substantia nigra." (PMID 26150767, 2015). "Also, several pieces of evidence indicate that TNF-α is an important player in the state of insulin resistance observed during obesity which in turn contributes to several pathological problems of obese patients such as hyperlipidemia, arteriosclerosis and hypertension." (PMID 25762868, 2015). "Thus, exacerbation of TNF-α-induced ET-1 synthesis could be one mechanism whereby obesity or specific metabolic factors may amplify the arterial pressure response to RUPP." (PMID 26569331, 2015). "Interestingly, TNF-α-induced skeletal muscle oxidative stress has been shown to be prevented by antioxidant treatment, suggesting that TNF-α may provide a vital target toward correcting obesity-related oxidative stress." (PMID 26435910, 2015). "It is believed that overproduction of TNF-α in obesity is an ultimate attempt to control adiposity, since increased TNF-α may help at limiting further weight gain through lipolysis and insulin resistance, impaired preadipocyte differentiation and increased adipocyte apoptosis." (PMID 25789857, 2015). "Transgenic mice with Dnmt3a overexpression display increased inflammation after HFD that is accompanied by increased expression of the tumor necrosis factor-α (TNF-α) and the monocyte protein-1 (MCP-1); increased Dnmt3a expression may also contribute to inflammatory-associated obesity." (PMID 26690877, 2015). "Lowered TNF-α after exercise might have an important role in the obesity reduction." (PMID 26075288, 2015). "Also, it is possible that a chronic elevation of plasma TNF-α—as observed in, for example, obesity—might affect β-cell function over longer time." (PMID 24692847, 2014). "The links between obesity, insulin resistance, and immune function have provided the basis for the emerging field of immunometabolism which implicates immune cell infiltration and increased expression of inflammatory mediators such as TNFα and IL‐1β in the pathophysiology of metabolic disease." (PMID 25096554, 2014). "Indeed, this type of adipose tissue is able to produce proinflammatory cytokines, such as tumor necrosis factor-alpha (TNF-alpha) and interleukin-6 (IL-6), and it is responsible of the increase of obesity-related CVD risk factors such as dyslipidemia, insulin resistance, and hypertension." (PMID 24966465, 2014). "It is thought that the impaired actions of TNF-α may lead to obesity." (PMID 25558907, 2014). "Therefore, it is tempting to speculate that these signals are also responsible for the induction of NKG2D ligands in the adipose tissue in vivo given that insulin and TNF-α levels are known to be elevated in obesity." (PMID 25333972, 2014). "Our finding suggests that obesity may contribute to the increase of serum TNF-α levels in cSLE." (PMID 24741576, 2014). "Also, TNF-α contributes to insulin resistance and hepatic steatosis in diet induced obesity." (PMID 25251155, 2014).
Obesity (continued). "Nevertheless, the Kv1.3 inhibitor margatoxin decreased TNFα secretion by white adipose tissue from genetically obese (ob/ob) mice, and administration of the highly selective Kv1.3 inhibitor ShK-186 for 45 days to mice fed on an obesity-inducing diet reduced TNFα mRNA in visceral adipose tissue." (PMID 25320682, 2014). "The present study investigates how obesity influences the immune response of septic patients, by assessing the number and activation state of adipose tissue macrophages, serum and adipose tissue tumor necrosis factor-alpha (TNFα) levels and plasma oxidative stress markers." (PMID 25244356, 2014). "With the development of obesity, adipose tissue is reported in humans and rodents to adopt a distinct inflammatory phenotype, characterized by increased gene expression and secretion of proinflammatory cytokines, such as tumor necrosis factor (TNF-α) and interleukins (IL)-1 and -6." (PMID 24977043, 2014). "The inflammatory milieu of obesity is complex, featuring a panoply of elevated plasma and tissue specific cytokines that are increased in some rheumatic diseases and are able to increase the expression of inflammatory cytokines, such as TNF and IL-6, also in the early phases of the disease." (PMID 25426122, 2014). "Notably, both TNF and sclerostin are increased in obesity and diabetes." (PMID 25140176, 2014). "Although TNFα is known to increase lipolysis in adipocytes, there is also evidence of a counterinflammatory response in obesity that may serve to repress energy expenditure." (PMID 24368730, 2013). "Furthermore, treatment of 3T3-L1 adipocytes with TNF-α induced MIF secretion, suggesting that TNF-α may regulate MIF production during obesity." (PMID 23675368, 2013). "TNFα promoter polymorphisms that augment TNFα expression are associated with an increased obesity-related risk of asthma, especially nonatopic asthma, suggesting that TNFα may also be relevant for obesity-related asthma." (PMID 23434795, 2013). "Also, studies have shown an increased inflammatory response associated with the presence of hyperleptinemia without obesity, and that leptin is able to control TNF-α production and activation by macrophages." (PMID 23593289, 2013). "Obesity is associated with decreased plasma adiponectin concentrations and a chronic low-grade inflammation characterized by increased adipose tissue expression of pro-inflammatory chemokines and cytokines such as MCP-1 and TNF-α, as well as infiltration of M1 (pro-inflammatory) macrophages." (PMID 23967184, 2013). "The pro-inflammatory cytokines TNFα and IL-6 have been shown to trigger phosphorylation of IRS-1, thus exerting an inhibitory action on insulin signaling; accordingly, genetic ablation either of TNFα or of its receptor can improve insulin resistance caused by obesity in rodent models." (PMID 23698776, 2013). "Despite the absence of obesity, they showed IR and a reduced adiponectin level associated to a high inflammatory state, elevated serum levels of pro-inflammatory cytokines, such as tumor necrosis factor α (TNFα), and interleukin (IL)-1β, IL-6, and IL-8." (PMID 24213605, 2013). "Furthermore, treatment with an anti-TNF-α mAb largely reduced the allergic pulmonary eosinophilic inflammation in obese mice placing an important role for this cytokine in the asthma aggravation by obesity." (PMID 24204674, 2013). "Hotamisligil and colleagues showed early on there is a substantial increase in expression of the pro-inflammatory cytokine tumor necrosis factor (TNF)α in several rodent models of obesity and that neutralizing TNFα could improve insulin-sensitivity in these animals." (PMID 23964195, 2013). "Mice with diet-induced obesity exposed to oral infection or systemic inoculation of live Porphyromonas gingivalis (P. gingivalis) developed a blunted inflammatory response with reduced expression of TNF, IL-6, and serum amyloid protein A (SAA) when compared with lean mice." (PMID 23922979, 2013).
Obesity (continued). "In obesity-related high plasma leptin conditions, inflammation occurs when signal transduction pathways are activated, such as activation of NFκβ, by the binding of leptin to its receptor (Ob-R), and subsequent release of the inflammation factors, for instance tumour necrosis factor alpha (TNFα)." (PMID 23856194, 2013). "It is widely accepted that obesity is characterized by evidence of a chronic, low-grade inflammatory process, as manifested by elevated circulating levels of acute phase proteins and cytokines, such as tumor necrosis factor α (TNFα), interleukin 1 (IL-1), and IL-6." (PMID 23967297, 2013). "However obesity, a potent contributor to IR, may limit the beneficial effects of anti-TNFα medication on IR." (PMID 22765047, 2012). "However, obesity - a potent contributor to IR in the general population - might influence the way anti-TNFα therapy affects IR." (PMID 22765047, 2012). "Surprisingly, the high carbohydrate diet slightly restored the protective effect of IPostC in the TNF-deficient mice, therefore suggesting that absence of TNFα in obesity may be of benefit to the heart." (PMID 23125848, 2012). "However, a slight protection with IPostC was observed in our TNF−/− model in the presence of obesity, illustrating the bidirectional effect of TNFα in the heart and the fact that the role of TNFα in obesity- and diabetes-related ischaemic heart disease remains a complex system." (PMID 23125848, 2012). "Since IL-10 and TNF-α are expressed and released mainly from the stromal vascular fraction of the adipose tissue, these findings provide further evidence for altered inflammatory activity of immune cells in the epididymal fat depot of mice with long-standing obesity." (PMID 22051061, 2011). "Importantly, obesity is associated with chronic low-grade inflammation, and a high-fat diet increases the proinflammatory cytokines IL1-β, tumor necrosis factor alpha (TNF-α), C-reactive protein (CRP), and IL1-6 and stimulates inflammatory signaling in adipose, serum, liver, and brain." (PMID 22144990, 2011). "Moreover, the observation that increases in intestinal TNF-α precede yet significantly correlate with body weight gain, body fat, and subsequent development of insulin resistance, supports a potential role of gut-derived TNF-α in the development of HF-induced obesity and obesity-related disease." (PMID 22115311, 2011). "Furthermore, TNFα decreases adiponectin expression and stimulates the secretion of proinflammatory proteins (for example, IL-6), which contribute to the maintenance of the chronic inflammatory state of adipose tissue in obesity." (PMID 21410966, 2011). "Of note, in patients with COPD, increases in IL-6 and TNF-α in the systemic circulation have been linked to obesity and insulin resistance; nevertheless, no reports analyzed the role of inflammation within the adipose tissue itself in metabolic derangements in such patients." (PMID 21197447, 2010). "On the other hand, increased leptin levels are associated with increased concentrations of other proinflammatory cytokines such as IL-1, IL-6, IL-8, TNFα, and prostaglandin E2, which may provide more specific and selective approaches for pharmacologic intervention in obesity-induced osteoarthritis." (PMID 20604941, 2010). "Increased mRNA expression of TNF-α, IL-1 and IL-6 has been reported in the kidney of streptozotocin-induced type 1 diabetic rats, a model associated with much higher levels of plasma glucose and no obesity." (PMID 20490358, 2010). "Therefore, increased TNF−α might be partially responsible for the decreased adiponectin production in obesity." (PMID 21274300, 2009). "TNFα plays a main role in the inflammatory state that is characteristic of obesity, and the increase in its levels may be related with the inhibitory effect on insulin receptor signalling pathway, the diminishing triacylglycerol depots in adipose tissue or in the development of apoptosis." (PMID 17725831, 2007).
Obesity (continued). "Interestingly, TNFα is not only expressed in macrophages, lymphocytes, neutrophils, endothelial cells, keratinocytes and fibroblasts but is also expressed in adipose tissue and is elevated in a number of experimental obesity models and obese humans." (PMID 18070349, 2007). "Alternatively, TNFα may induce accelerated atherogenesis in obesity by other mechanisms." (PMID 16803616, 2006). "Moreover, M1 macrophages inhibit the activity of lipolytic enzymes (such as ATGL) by secreting TNF-α, thereby disrupting lipid storage homoeostasis; activation of the EPAC2–ST2 pathway may further reinforce this process, which is associated with obesity-related metabolic disorders." (PMID 41503874, 2026). "Western blot analysis revealed that, compared with controls, the protein expression levels of GLUT4 and p-IRS1 were markedly decreased in the obesity group (P < 0.0001), whereas HIF-1α and TNF-α protein levels were significantly increased (P < 0.0001)." (PMID 41505418, 2026). "Aerobic and resistance training programs up to 4 months resulted in a decrease in scWAT inflammatory gene expression such as IL-6, IL-8, and TNF-α and CD36 macrophage marker in patients with obesity or those over 71 years of age." (PMID 40522819, 2025). "Obesity is strongly correlated with inflammatory biomarkers, such as CRP, interleukin‐6 (IL‐6), and tumor necrosis factor‐alpha (TNF‐α), both IL‐6 and TNF‐α are produced by adipocytes and act as adipokines and inflammatory markers." (PMID 40551726, 2025). "In obesity, the inflammatory milieu, including saturated fatty acids engaging TLR4 receptors and cytokines like TNF-α, promotes classical M1 macrophage polarization." (PMID 41463063, 2025). "In patients with obesity, insulin resistance can be triggered by WAT inflammation, as WAT inflammation leads to the release of pro-inflammatory cytokines, such as TNFα, IL-1β, IL-6, that inhibit insulin signaling and impaired glucose uptake." (PMID 40456448, 2025). "For TNFα, two-way ANOVA revealed significant effects of obesity (F = 14.87; p = 0.0048), OEA-DS administration (F = 6.188; p = 0.0377), and the interaction of these factors (F = 15.03; p = 0.0047)." (PMID 40265441, 2025). "In particular, TNF-α, IL-6, and CRP are reported to be significantly high in the circulation of pregnant women with obesity or GDM." (PMID 40278381, 2025). "Biomarkers, such as ferritin, leptin, resistin, interleukin-6 (IL-6), insulin, tumor necrosis factor-alpha and plasminogen activator inhibitor-1 (PAI-1), play crucial roles in the pathophysiology of obesity." (PMID 41011232, 2025). "Obesity also contributes to the production of inflammatory molecules such as interleukin-6 (IL6) and tumor necrosis factor-α (TNFα), favoring the creation of an environment useful for MPNs’ progression." (PMID 40725771, 2025). "In addition, muscle IL-6 modulates the immune response by inhibiting TNF-α production and stimulating anti-inflammatory cytokines such as IL-10 and IL-1ra, which favors the reduction of chronic low-grade inflammation observed in pathologies such as obesity and type 2 diabetes." (PMID 40648864, 2025). "Obesity and metabolic syndrome frequently trigger a systemic inflammatory response; consistently, the analysis of circulating pro-inflammatory cytokines (TNF-α, IL-6, IL-17) demonstrated that HFD exposure increased TNF-α levels and that such an increase could be counteracted by JQ1." (PMID 38365172, 2025). "Elevated levels of inflammatory mediators, such as tumor necrosis factor alpha (TNF-alpha), interleukin-6 (IL-6), and C-reactive protein (CRP), are observed in obesity." (PMID 40218888, 2025). "In conditions of cardiometabolic dysfunction and obesity, PVAT secretes pro-inflammatory cytokines, such as leptin, MCP-1, and TNF-alpha, that lead to proatherogenic states, concepts which have been previously reviewed." (PMID 41155468, 2025).